VEGFA (vascular endothelial growth factor A)
Diseases named in the same sentence as VEGFA in open-access papers (continued):
Sharing a sentence is not in itself a finding about the gene and the disease.
tumor (continued). "It has been reported that aberrant splicing leads to an increase in proangiogenic isoforms of VEGFA and prompts tumor angiogenesis." (PMID 35198444, 2022). "For example, Bevacizumab is a monoclonal antibody that binds to vascular endothelial growth factor-A(VEGF-A)which is highly expressed in tumor cells and plays a direct role in vascular endothelial production." (PMID 35860548, 2022). "VEGFA acts as the main mediator of tumor angiogenesis, stimulates the growth of new blood vessels in nearby capillaries, and allows tumors to obtain oxygen and nutrients needed for growth." (PMID 35468741, 2022). "Thymus stromal lymphopoietin derived from tumour cells can increase the expression of VEGFA, thereby inducing angiogenesis." (PMID 35464051, 2022). "VEGFA secreted by tumour cells promotes an epithelial-to-mesenchymal transition phenotype, consequently inducing tumour invasion." (PMID 35109839, 2022). "Tumor-derived VEGFA, along with other pro-angiogenic factors, can recruit and activate immune and stromal cell populations that are involved in physiological wound healing; they are recruited to “heal” the tumor." (PMID 35577211, 2022). "The VEGF/VEGFR signaling pathway is thought to promote tumor angiogenesis, growth, invasion, and metastasis, and the activation of VEGFA expression can promote GC growth and angiogenesis." (PMID 35462892, 2022). "For the angiogenesis during tumor progression, the effects of VEGFA are considered to be implemented mainly via extracellular secretion." (PMID 34975330, 2022). "To test this possibility, we first intradermally injected recombinant VEGFA and verified that both angiogenesis and tumour growth were markedly increased." (PMID 36450983, 2022). "RNA sequencing (RNA-seq) identified 715 upregulated and 629 downregulated transcripts (including VEGFA) in tumor tissues of mice in the swimming group." (PMID 35291563, 2022). "VEGFA has been identified as a therapeutic target of tumor angiogenesis for decades 69 and has been reported to be associated with promoted EMT progression in various cancer types." (PMID 34975330, 2022). "Vascular endothelial growth factor A (VEGFA) is a major driver of angiogenesis during tumor progression in various cancers." (PMID 35769999, 2022). "It is established that lncRNAs function as ceRNA to increase VEGFA expression by competing with miRNAs, resulting in tumor angiogenesis." (PMID 35562342, 2022). "Other two high-ranking hub proteins (HNRNPA1 and VEGFA) were also proved to play a vital role in tumor cell biology." (PMID 36147313, 2022). "VEGFA-modulated neoangiogenesis has been connected to the EMT-triggered tumor initiation from cancer stemness." (PMID 35203290, 2022). "In PDX1, T-DM1 treatment, which reduced tumor growth, resulted in a significant decrease in the number of cluster 2 cells, characterized by high VEGFA expression (P = 3.69 × 108)." (PMID 33886505, 2021). "hsa-miR-29b-3p was the most significantly expressed in the tumour tissues and regulated two hub genes, VEGFA and TPM1." (PMID 34112125, 2021). "For example, LncRNA‐TUG1 constitutes a regulatory network with miR‐34a‐5p and VEGFA that participates in the regulation of HB cell function, tumour progression and tumour angiogenesis." (PMID 33683826, 2021). "The M2d subtype, also known as tumor‐associated macrophages (TAMs), secretes TNFα, IL‐6, IL‐10, TGFβ, and VEGFA to promote tumor progression." (PMID 34136188, 2021). "Contribution of secreted full-length mRNA in GBM tumor progression and the release of extracellular vesicles containing pro-angiogenic functional cargo, comprising VEGFA mRNA, by GBM cells have also been ascertained." (PMID 33562358, 2021). "In our study, we discovered the regulatory role of miR-152-3p in the lncRNA PVT1/VEGFA axis, especially exosomes, which are closer to the exploration and application of tumor microenvironment." (PMID 34336125, 2021).
tumor (continued). "Our findings are consistent with results from studies of PDX models in other cancers where tumor cells were shown to be the major source of VEGFA while PlGF was primarily produced by tumor stroma." (PMID 34198773, 2021). "Targeting XBP1 inhibits the ability of pro-tumor cytokines, such as IL-6 and VEGFA, as well as promotes tumor growth and metastasis." (PMID 34667145, 2021). "VEGFA is the most significant mediator of tumor angiogenesis, increases vascular permeability and microvascular density." (PMID 34298612, 2021). "The internal mechanism of miR-29a-3p and VEGFA in regulating EC development was verified by in vitro rescue experiment and in vivo xenograft tumor experiment." (PMID 34289832, 2021). "To further confirm the underlying mechanism by which BAF312 inhibits tumor growth and antivascular formation, we conducted immunohistochemical analysis, and the results indicated that S1PR1, P-STAT3, and VEGFA were downregulated." (PMID 34059068, 2021). "The results indicated that the expression of tumor cell-derived VEGFA, IGFBP3, EFNA1, EFNB1, IGF2, PDGFA and stroma-derived Angpt2, Cdh5, Esam, Esm1, Icam2, and Tie1 was statistically correlated with that of Pecam1 and elevated in p-EMT TW2.6 tumors." (PMID 34869001, 2021). "After that, MSCs are differentiated into CAFs and tumor cells, and the VEGFA gene is expressed in CAFs and tumor cells." (PMID 34397824, 2021). "As an oncoprotein, YB-1 has been reported to relocate to the nucleus to promote tumor development and extensively to regulate the expression of VEGFA in various mechanisms at transcription levels." (PMID 34306080, 2021). "Under hypoxic conditions, EGR1 increases VEGFA expression, mediated by HIF1α, and directly activates VEGFA transcription, thus promoting the formation of blood and lymphatic vessels in the tumor." (PMID 33842351, 2021). "In 1993, the finding that a monoclonal antibody can target and neutralize VEGFA and inhibit tumour growth in the xenograft model led to the translational possibility for targeting VEGF‐VEGFR signalling." (PMID 33655556, 2021). "The most key triggering factors of angiogenesis in a tumor tissue include MMPs, vascular endothelial growth factor-A (VEGF-A), fibroblast growth factor (FGF), hepatocyte growth factor (HGF), and PlGF." (PMID 33685452, 2021). "Functionally, ACE2 can suppress tumor proliferation, invasion, angiogenesis, and metastasis by downregulating the expression of Ang II and vascular endothelial growth factor a (VEGFa)." (PMID 34221978, 2021). "VEGFA plays an important role in controlling cell survival, growth, differentiation, adhesion, migration, tumor angiogenesis, wound healing, and tissue repair." (PMID 34423029, 2021). "The direct target gene of miR-29a is VEGFA, so the sponging of miR-29a by circMYLK inhibits the tumor-suppressive role that it plays." (PMID 34162394, 2021). "In order to facilitate angiogenesis, cancer cells frequently overexpress pro‐angiogenic factors, for example, vascular endothelial growth factor‐A (VEGFA), thereby positioning anti‐angiogenic agents as potential strategies for tumor therapy." (PMID 33314660, 2021). "It was reported that VEGFA is a potential neovascular regulatory factor that promotes tumor growth and metastasis through its receptor." (PMID 33557781, 2021). "Vascular endothelial growth factor-A (VEGF-A) derived from tumors and host mesenchymal tissues plays an essential role in tumor progression by promoting angiogenesis mainly through its receptor VEGF receptor 2 (VEGFR2) expressed in vascular endothelial cells." (PMID 34302038, 2021). "Angiogenesis/neovascularization is a major cancer hallmark, and the vascular endothelial growth factor-A (VEGF-A), which is produced in the tumor cells by tumor-associated macrophages and fibroblasts, plays an important role as an angiogenesis-inducer." (PMID 34358082, 2021). "Tumor angiogenesis induced by vascular endothelial growth factor A (VEGF-A) plays an important role in tumor growth." (PMID 33750370, 2021).
tumor (continued). "In the last two decades, inhibition of vascular endothelial growth factor A (VEGFA) signaling to target tumor endothelia evolved as a new concept for tumor therapy." (PMID 34359800, 2021). "The short-term efficacy, common clinical indicators, tumor indicators, changes in serum vascular endothelial growth factor-A (VEGF-A), and the occurrence of adverse events (AEs) were explored after treatment." (PMID 34485157, 2021). "Bevacizumab is a monoclonal antibody and, besides its well-known inhibitory effect on tumor angiogenesis, attenuates VEGFA-mediated signaling in complicated lymphatic anomalies (CLAs)." (PMID 34660476, 2021). "High expression of VEGFA is reported to impair infiltration of effective anti-tumor T-cells, thus leads to innate resistance in PD-1/PD-L1 blockade." (PMID 33562324, 2021). "These TAMs within hypoxia regions express higher vascular endothelial growth factor A (VEGF-A) levels than TAMs located in other tumor regions, contributing to angiogenesis and faster-growing tumors." (PMID 33919979, 2021). "Vascular endothelial growth factor A (VEGF) is the primary mediator of angiogenesis, and VEGF directly contributes to targeting tumor cell growth and metastasis." (PMID 34876130, 2021). "A previous study confirmed that the activation of dNK cells through repeated pregnancies led to increased production of VEGFa, supporting vascular sprouting and tumor growth." (PMID 34803505, 2021). "According to the ELISA experimental data, tumor cells were able to secrete VEGFA and TNFSF11 (RANKL)." (PMID 34367994, 2021). "While many HDAC4 targets have been identified, we focused on HIF1α, one of the central players of tumor progression and drug response and VEGFA, one of the best-characterized HIF1α targets." (PMID 34359722, 2021). "Overall, these data suggest that TMEM doorways within the dissemination trajectories reflect to TMEs with high VEGFA expression and activity, suggesting that they function as candidate beacons of endothelial anergy within the tumor microenvironment." (PMID 33927723, 2021). "In tumor cells of cHL canonical WNT/β-catenin/LEF-1 signaling is also required to secrete vascular endothelial growth factor A (VEGF-A), and by that, to attract endothelial cells as well as to enhance their migration, sprouting and tube formation." (PMID 34778050, 2021). "The JAK/STAT pathway sustains tumour growth also by promoting angiogenesis: vascular endothelial growth factor A (VEGFA) and hypoxia-inducible factor 1 α (HIF-1α) are target genes of STAT." (PMID 34201209, 2021). "Vascular endothelial growth factor A (VEGFA) is one of the main mediators of angiogenesis, secreted by tumor cells, together with platelet-derived growth factor (PDGF), and epidermal growth factor (EGF)." (PMID 34208346, 2021). "GBMs are characterized by increased microvascular proliferation, which is essential for tumor growth and invasion, that is mainly mediated by vascular endothelial growth factor A (VEGF-A) signaling." (PMID 34253243, 2021). "In tumor-related angiogenesis, VEGFA-based response mediates numerous functional effectors, including phosphoinositide 3 kinase (PI3K)/Akt, p38 MAPK, and ERKs." (PMID 34603055, 2021). "Ablation of XBP1 inhibited the expression of the pro-tumor cytokine signature of TAMs, including IL-6, VEGFA, and IL-4." (PMID 34667145, 2021). "There is evidence to indicate that miR-206 targets the VEGFA/CCL2 signaling pathway to inhibit tumor progression." (PMID 34697590, 2021). "Earlier research indicated that the STAT3 protein binds to the VEGFA promoter in vivo and found that constitutive STAT3 activity upregulates VEGFA expression and tumor angiogenesis." (PMID 34059068, 2021). "Vascular endothelial growth factor-A (VEGF-A), which promotes tumor angiogenesis, is another critical target." (PMID 34503155, 2021). "VEGFA mediates angiogenesis and vasculogenesis by regulation of endothelial cells and acts as a pro-survival factor of endothelial cells during tumor angiogenesis." (PMID 33690729, 2021).
tumor (continued). "VEGFA is a member of the PDGF/VEGF growth factor family that plays an essential role in tumor angiogenesis and is expressed in undefined cells-1." (PMID 34397824, 2021). "MiR-299-3p is a tumor suppressor miRNA that inhibits progression of prostate cancer by modulating androgen receptor and VEGFA signaling pathways." (PMID 33535182, 2021). "Tumour subtype specificity on Wnt, Notch, VEGFA-VEGFR2 and PI3K-Akt-mTOR in TN and cytokines in ER+ were observed." (PMID 34193143, 2021). "It is known that VEGFA has a crucial role in BC tumorigenesis through its effects on tumor angiogenesis." (PMID 34359591, 2021). "VEGFA signaling from TIE2-expressing macrophages induced local loss of vascular junctions and transient vascular permeability, stimulating tumor cell intravasation." (PMID 34884995, 2021). "VEGFA, as a tumor angiogenic factor, also plays a pivotal role in the formation of the tumor immunosuppressive microenvironment." (PMID 33407585, 2021). "Global alterations of AS have been shown to occur in cancer cells, including deregulated splicing of critical regulators of tumor angiogenesis such as vascular endothelial growth factor A (VEGF-A)." (PMID 34433435, 2021). "These EVs, released in response to cisplatin, can stimulate the migration of MSCs and increase the secretion of IL-6, IL-8, and VEGFA, thus stimulating a more aggressive and tumor-promoting phenotype in MSCs." (PMID 34440886, 2021). "Tumor angiogenesis is driven primarily by hypoxia; in hypoxic conditions, cancer cells secrete VEGFA, which engages the VEGFR2 receptor on nearby vascular endothelial cells, stimulating the growth of new vascular sprouts." (PMID 33924982, 2021). "PI3K activation promotes vascular endothelial growth factor-A (VEGF-A) expression leading to angiogenesis, a key component of tumor growth and metastases." (PMID 34938658, 2021). "Research confirmed VEGFa in tumor cells would be bind to VEGFR2 on the membrane of adjacent endothelial cells." (PMID 34413267, 2021). "Heparin–taurocholate conjugate (HT10) or heparin–DOCA conjugate (H-DOCA) were shown to inhibit tumor growth and metastasis while regulating the activity of tumor-related growth factors such as vascular endothelial growth factor A (VEGF A)." (PMID 34638867, 2021). "VEGFA is significantly upregulated in many cancers and is essential for tumour proliferation, invasion and metastasis." (PMID 34112125, 2021). "In particular, VEGFA is a major player in physiological and tumor-induced angiogenesis, and numerous human tumors, including GBM, have shown VEGFA overexpression." (PMID 34660561, 2021). "Evaluating hallmark pathways in the VEGFA+ C4 cluster and other clusters from EPN by gene set variation analysis (GSVA) revealed a strong enrichment of angiogenesis and hypoxia in the VEGFA+ C4 cluster, suggesting its high capacity to favor tumor progression." (PMID 34824203, 2021). "CCL20+ TAMs can also secrete tumour necrosis factor-alpha (TNFα) and vascular endothelial growth factor-A (VEGF-A), contributing to tumour growth and angiogenesis." (PMID 34830780, 2021). "This interaction seemed to be mediated through reduced expression of vascular endothelial growth factor-A (VEGF-A) by tumor cells and integrin expression by endothelial cells." (PMID 34944095, 2021). "Vascular endothelial growth factor A (VEGFA) and its receptors have been identified as major mediators of angiogenesis, which is crucial for tumor invasiveness." (PMID 34944753, 2021). "HIFs are key players in tumor aggressiveness and drug resistance particularly through Vascular Endothelial Growth Factor-A (VEGFA)-dependent angiogenesis and VEGFC-dependent lymphangiogenesis." (PMID 33461580, 2021). "Genetic inactivation of VEGFA in MDSCs improved clearance of senescent tumor cells by NK cells, inhibited tumor regrowth after chemotherapy and, prevented cachexia in tumor-bearing mice." (PMID 34025641, 2021).
tumor (continued). "MC can however also promote the growth of Hodgkin’s tumours by modifying the tumour ME with the release of vascular endothelial growth factor-A and the induction of neovascularization." (PMID 34298847, 2021). "The overexpression of IL1A can, in turn, stimulate the transcription of growth factors such as MMP1 or VEGFA, both found upregulated in our tumor samples, possibly creating a proper environment for carcinogenesis." (PMID 34638231, 2021). "VEGFA, also known as VEGF, is a growth factor that promotes tumor angiogenesis and vascular permeability and regulates immune cell and fibroblastoma and microenvironment formation." (PMID 34394352, 2021). "EIF4A3 inhibition not only reduces tumor proliferation, migration, and angiogenesis, but it also shortens the half-life of VEGFA, suggesting that LINC00667-VEGFA-EIF4A3 is an oncogenic pathway in NSCLC." (PMID 34458150, 2021). "Reprogrammed fibroblasts then upregulate the expression of several angiogenic factors, including VEGFA, which stimulate the remodelling of tumoural blood vessels." (PMID 33572413, 2021). "Perivascular cells induce VEGFA production to activate survival signalling in endothelial cells through an autocrine mechanism, which protects tumour vessels from antiangiogenic drugs." (PMID 34035882, 2021). "IL‐36α suppresses tumor growth by inhibiting tumor angiogenesis via suppression of hypoxia‐inducible factor‐1α/vascular endothelial growth factor A signaling." (PMID 33713575, 2021). "Eventually, FOXM1D‐induced VEGFA release in the exosome strongly promotes tumor angiogenesis and progression." (PMID 33314660, 2021). "It has been proved that TGF-β induces angiogenesis by regulating VEGFA expression for the spread and tumor metastasis, which is, in part, inhibited by Tranilast." (PMID 34452560, 2021). "VEGFA is one of the most potent proangiogenic factors, which is closely involved with angiogenesis in the tumor microenvironment and significantly promotes tumor growth." (PMID 33713575, 2021). "Analysis showed that PRMT3 regulates HIF1/VEGFA signaling pathway and tumor angiogenesis by methylating HIF1α R282 and promoting stability of HIF1α." (PMID 34753906, 2021). "TMB with hypoxia and hyper-angiogenesis is obviously crucial for tumor growth and progression, and vascular endothelial growth factor A (VEGFA) plays a significant role in it." (PMID 33562324, 2021). "Real-time imaging revealed that local and transient vascular permeability and tumor cell intravasation are stimulated by Tie2+ macrophage-derived VEGFA." (PMID 34572013, 2021). "Gerber and colleagues identified hypoxic MESO at milky spots secreting vascular endothelial growth factor (VEGFA) suggesting that factors produced by MESO promote the growth of metastatic tumour cells by inducing neo‐angiogenesis." (PMID 34841720, 2021). "In tumor tissues, a variety of cells can produce VEGFA, such as cancer cells, endothelial cells, and tumor-associated macrophages." (PMID 34226531, 2021). "Followed functional experiments indicated that overexpression of LINC00941 accelerated angiogenesis and NSCLC tumor progression via miR-877-3p/VEGFA axis both in vitro and in vivo." (PMID 33869051, 2021). "As far as esophageal squamous carcinoma was concerned, lncRNA AFAP1-AS1 decreased suppressive influence of miR-498 on protein levels of VEGFA, thereby delaying apoptosis of the tumor cells." (PMID 34289449, 2021). "Previous studies have stated that tumor angiogenesis was promoted by ERO1A via regulating the expression of VEGFA." (PMID 34712608, 2021). "VEGFA is secreted by tumour cells and stroma and is the most studied inducer of tumour angiogenesis; its presence is correlated with tumour size, blood vessel density and metastasis." (PMID 33572413, 2021). "High plasma levels of VEGFA, an important angiogenic factor, had a positive correlation with advanced tumour stages in BC patients." (PMID 34791795, 2021).